CDK8 (cyclin dependent kinase 8)
Diseases named in the same sentence as CDK8 in open-access papers (continued):
Sharing a sentence is not in itself a finding about the gene and the disease.
colon carcinoma (continued). "CDK8 has been found to be amplified and over expressed in colon cancer." (PMID 31384837, 2019). "In this context, CDK8 has been reported to act as a colon cancer oncogene." (PMID 31384837, 2019). "Thus, in addition to its role as a CRC oncogene in driving Wnt/β–catenin signaling in invasive colon cancers, CDK8 acts as a tumor suppressor presumably in early stages of intestinal tumorigenesis." (PMID 30693281, 2018). "Cyclin-dependent kinase 8 (CDK8) is an oncogene that couples transcriptional regulators to the basal transcriptional machinery, and is implicated in the transcriptional regulation of key pathways involved in colon cancers." (PMID 28430641, 2017). "However suppression of CDK8 expression inhibits proliferation in colon cancer cells characterized by high levels of CDK8 and β-catenin hyperactivity." (PMID 25625291, 2015). "Likewise, increased expression of a CDK8-regulated, embryonic stem cell MYC target gene signature was associated with loss of differentiation and poor outcome in primary human colon cancers." (PMID 25625291, 2015). "Colorectal cancers with CDK8 expression have distinct clinical, prognostic and molecular attributes and both CDK8 and β-catenin levels have been reported to correlate with carcinogenesis, tumor progression and increased colon cancer-specific mortality." (PMID 25625291, 2015). "For example, CDK8 plays an important regulatory role in biological processes at the transcription level in the Wnt/β-catenin signaling pathway and it is proposed to be a proto-oncogene in human colon cancer." (PMID 26286725, 2015). "According to our results, it was speculated that the possibility of the regulation of colon cancer through control of CDK8 is theoretically applicable." (PMID 22104393, 2011). "Our results showed that CDK8 and β-catenin could be promising target in the regulation of colon cancer by the control of β-catenin through CDK8." (PMID 22104393, 2011). "Based on the high specificity of CDK8 to β-catenin, CDK8 may be used as an alternative target in the regulation of colon cancer." (PMID 22104393, 2011). "CDK8 and β-catenin were expressed in colon cancer at a high frequency." (PMID 22104393, 2011). "Accordingly, it is indicated that the intervene stategy targeting CDK8 in colon cancer may be of clinical value." (PMID 22104393, 2011). "Taken together, CDK8 plays an important regulatory role in cell cycle control and cell growth at the transcription level and it is proposed to be a proto-oncogene in human colon cancer." (PMID 22104393, 2011). "In addition, we verified the mRNA and protein expression levels of CDK8 and β-catenin in colon cancer tissues." (PMID 22104393, 2011). "We suggest that CDK8-siRNA transfection may decrease cell proliferation and facilitate apoptosis of colon cancer cells." (PMID 22104393, 2011). "Interestingly, CDK8 stimulates expression of MMP-9 in human colon cancer cells via Wnt/β-catenin-driven transcription, while MED12 plays an important role in regulating and mediating the function of CDK8 kinase module, and the activation of CDK8 kinase also requires the participation of MED12." (PMID 35456498, 2022). "For instance, CDK8 assumes a critical regulatory role in biological processes at the transcriptional level in the Wnt/β-catenin pathway and may be a proto-oncogene in human colon cancer." (PMID 34362882, 2021). "In addition, CDK8 has been found to affect the activity of β-catenin in human colon cancer." (PMID 26286725, 2015). "Interference of CDK8 might be an effective strategy through β-catenin regulation of colon cancer." (PMID 22104393, 2011).
colon carcinoma (continued). "The CDK8-mediated direct phosphorylation further enhances YAP activation, thereby promoting colon cancer migration." (PMID 38606172, 2024). "CDK8 is known to phosphorylate E2F1 and to repress its transcriptional activity and this results in upregulated β–catenin protein in colon cancer cells." (PMID 33291686, 2020). "Since the initial suggestion that CDK8 is an oncogene relevant to colon cancer and may play a role in other types of tumors including breast tumors, we attempted to compare the effects of CDK8 inhibitor 4 on colon cancer cell lines and the TNBC cell line MDA-MB-468." (PMID 33291686, 2020). "Treatment of the colon cancer cell line Colo 205 and the TNBC cell line with inhibitor 4 resulted in decreased STAT1 phosphorylation (pSTAT1), indicating inhibition of CDK8 in all these cell lines, as expected." (PMID 33291686, 2020). "CDK8 phosphorylates and inhibits E2F1, an inhibitor of β-catenin function, resulting in increased activity of the Wnt/β-catenin pathway in colon cancer cells and suppression of CDK8 expression in these cells inhibits proliferation." (PMID 25914884, 2015). "In contrast to the single knockouts,double knockout clones were completely unresponsive to CCT251921 treatment(T/C: 113 ± 10%, p < 0.005), demonstrating that inhibitionof both CDK8 and CDK19 is required to slow or arrest growth in theSW620 colon cancer xenograft model." (PMID 40601435, 2025). "CDK8 has been reported to be overexpressed in colon cancer, and inhibition of CDK8 did not affect colon cancer cell growth but significantly suppressed colon cancer liver metastasis." (PMID 34067719, 2021). "Here, we describe the preliminary results of our investigations aimed at understanding the cell biological effects of CDK8 inhibitor 4 on triple-negative breast cancer (TNBC) cell line MDA-MB-468 compared to both APC mutant and β–catenin mutant colon cancer cell lines Colo205 and HCT116." (PMID 33291686, 2020). "In addition, Cdk8 has been shown to activate the oncogene YAP through direct phosphorylation, leading to colon cancer tumorigenesis." (PMID 30621145, 2019). "Although CDK8/CDK19 kinase inhibition has no significant impact on the proliferation of colon cancer cells, it effectively suppresses hepatic metastasis, even when already established." (PMID 31248103, 2019). "While the linkage of CDK8 to carcinogenesis was originally discovered in colon cancer, CDK8/19 kinase inhibitors did not inhibit the growth of CDK8-overexpressing colon cancer cells." (PMID 28147342, 2017). "Meanwhile, it is reported that the expression of β-catenin was still positive or high in some colon cancer cell lines that have negative expression of CDK8." (PMID 22104393, 2011). "Using paired samples of primary and brain metastasis colon cancer from the same patients in two recent studies, we demonstrated that the CDK8 amplification is not a newly emerged event in the brain metastasis but inherited from the primary tumors (12 out of 14)." (PMID 34795255, 2021). "In addition to this difference between microarray and RNA-Seq databases, regulation of CDK8 expression at protein level in colon cancers cannot be ruled out." (PMID 31382571, 2019). "Among the GI tract cancers, CDK8 was amplified much more frequently than CDK19 or CCNC, with no amplification of CDK19 or CCNC found in colon cancers (not shown)." (PMID 31382571, 2019). "It remains unknown whether CDK8 controls MYC phosphorylation directly or indirectly, however MYC has not been reported to be a substrate for CDK8 in human colon cancer cells." (PMID 30693281, 2018).
colorectal cancer (40 papers, 2010 to 2026). A primary or metastatic malignant neoplasm that affects the colon or rectum. "Cyclin-dependent kinase 8 (CDK8) has been identified as an oncogene that is associated with a reduced survival rate in colorectal cancers." (PMID 39619695, 2024). "CDK8 was foundto be an oncoprotein associated with the development of colorectal cancer, tumors of the pancreas and mammary glands, and melanoma.CDK8 is responsible for the phenotype of cancer stem cells." (PMID 33959383, 2021). "The oncogenic effects caused by gained CDK8 in melanoma and colorectal cancers have spurred an interest to develop CDK8-specific inhibitors for cancer treatment." (PMID 33053834, 2020). "Colorectal cancer cells expressing an ATP analog sensitivity CDK8 variant (CDK8- AS) exhibited growth defects and anti-tumorigenic properties both in vitro and in vivo in the presence of ATP analog 3MB-PP1." (PMID 30693281, 2018). "Of the 19 type-specific mutated genes, CDK8 has been established as a colorectal cancer oncogene that regulates beta-catenin activity and CDK5RAP1 located on the melanoma-susceptibility region." (PMID 22691569, 2012). "Notably, CDK8 is a prospective therapeutic target in colorectal cancer, and inhibition of the kinase is associated with reduced tumor growth." (PMID 40361480, 2025). "In our study, we found that in CRC, OXCT1 regulated CDK8 expression by inhibiting the histone acetylation in colorectal cancer cells." (PMID 41492470, 2026). "CDK8 is a key promoter of tumor in colorectal cancer (CRC) by modulating the Wnt/β-catenin signaling pathway." (PMID 40361480, 2025). "The CDK8 protein kinase, consisting of 464 amino acids, frequently exhibits amplification in colorectal cancer." (PMID 38606172, 2024). "In colorectal cancer, CDK8 phosphorylates E2F1 at the S375 site depending on its kinase activity rather than transcriptional activity, thus downregulating E2F1 transcriptional activity without affecting its protein stability." (PMID 38606172, 2024). "In colorectal cancer cells, impairing glucose transporter expression, glucose uptake, and glycolytic capacity in both normoxia and hypoxia can be achieved by using the CDK8/CDK19 inhibitor Senexin A or through the knockdown of CDK8." (PMID 38606172, 2024). "CDK8 was described as an oncogene in colorectal cancer where it promotes beta‐catenin‐dependent transcription, suggesting that its deletion should inhibit intestinal tumorigenesis." (PMID 36545778, 2023). "CDK8 has been attributed oncogenic functions in different cancers, including Wnt‐dependent colorectal cancer, melanoma, breast and prostate cancer, acute myeloid leukaemia, and B‐cell leukaemia." (PMID 36545778, 2023). "This showed a strong overlap with genes deregulated in knockout of Cftr as well as with genes downregulated in the human colorectal cancer cell line HCT‐116 upon treatment with a different CDK8/19 inhibitor, cortistatin A." (PMID 36545778, 2023). "CDK8 was found to act, in a kinase-dependent manner, as a driver of β-catenin-dependent transcription and colorectal cancer proliferation." (PMID 32961708, 2020). "CDK8 has been identified as a marker of poor prognosis for patients with advanced colorectal cancer." (PMID 33057364, 2020). "Several other Cdk8 inhibitors were proven effective against acute or chronic forms of leukemia, colon and colorectal cancer." (PMID 30621145, 2019). "Follow-up studies in patients with colorectal cancer demonstrated that upregulation of Cdk8 led to decreased survival." (PMID 30621145, 2019). "Previous studies found that CDK8 prevented apoptosis in pancreatic, melanoma and colorectal cancers." (PMID 30524203, 2018). "In particular, cyclin-dependent kinase 8 (CDK8) is a known colorectal oncogene, also located on 13q, and has been found to have increased copy number in 62% of colorectal cancers." (PMID 29501064, 2018).
colorectal cancer (continued). "As CDK8 is amplified and functions as an oncogene in colorectal cancer through the regulation of Wnt/β-catenin signaling, the therapeutic potential of the small molecules has been actively tested in preclinical models of colorectal and other cancers." (PMID 29568371, 2018). "Especially in colorectal cancer, CDK8 is frequently described to serve as an oncogene that regulates β-catenin activity suggesting a potential therapeutic value for CDK8 in colorectal cancer patients." (PMID 27050271, 2016). "In colorectal cancer, it is notable that the subunits of the kinase module, especially CDK8, exhibit enhanced expression (96%, n = 440/460)." (PMID 27050271, 2016). "In colorectal cancer, the highest overexpression rate was found for CDK8 with a frequency of 96% (n = 440/460)." (PMID 27050271, 2016). "Here, we also found that pharmacological inhibition of CDK8 with our potent and selective chemical probes in colorectal cancer models resulted in gene expression profiles consistent with increased super-enhancer activity." (PMID 27935476, 2016). "In addition, HIF-1α recruits cyclin-dependent kinase 8 to stimulate RNAPII elongation in colorectal cancer." (PMID 40484376, 2025). "Colorectal cancer patients with CDK8 over-expression also had a significantly worse prognosis." (PMID 39031216, 2024). "Additionally, CDK8 has been identified as an oncogenic driver in a variety of cancer types including melanoma, colorectal cancer, and hematological malignancies." (PMID 34689158, 2021). "Given that amplification or mutations of CDK8 have been identified in a variety of human cancers, such as colorectal cancer and lung neuroendocrine carcinoma, it is important to understand the function and regulation of CDK8 in different biological and pathological contexts." (PMID 33053834, 2020). "An shRNA screen has also demonstrated a requirement for CDK8 in the activation of WNT signaling in colorectal cancer, suggesting that CDK8 and the Mediator kinase module may promote oncogenesis through activation of the canonical WNT pathway." (PMID 27935476, 2016). "Furthermore, CDK8 expression is reportedly required for growth of colorectal cancer xenografts and to maintain embryonic stem cells in an undifferentiated state." (PMID 27935476, 2016). "CDK8 is a colorectal cancer oncogene and likely plays a role in tumorigenesis." (PMID 22428002, 2012). "Alternatively, the levels of Cdk8 itself may be rate-limiting as overexpression of Cdk8 has been found to regulate β-catenin levels in colorectal cancers." (PMID 20479885, 2010). "In addition to the amplification of the CDK8 (cyclin dependent kinase-8) gene, which is situated at 13q12.13 and is present in around sixty percent of cases of colorectal cancer, there are other genetic perturbations that have the ability to alter the activity of β-Catenin." (PMID 39031216, 2024). "In colorectal cancer, CDK8 may function as an oncogene by regulating β-catenin activity." (PMID 33686962, 2021). "CDK8 may act as an oncogene in colorectal cancer where CDK8 is amplified, with copy number gains observed in ~60% of tumors, and shRNA knockdown can reduce the growth of human colorectal cancer xenografts harbouring CDK8 gene amplification." (PMID 27935476, 2016). "Among the syntenic blocks between these regions, CDX2, CDK8, GSX1, and PDX1 are among candidate colorectal carcinoma and/or cancer driver genes affected by these recurrently gained chrs between human and mouse." (PMID 41051921, 2025). "We first expanded upon the existing time-to-progression model by testing combined ERK and CDK8/19 inhibition across diverse KRAS-mutant pancreatic, lung, and colorectal cancer cell lines." (PMID 38822082, 2024). "In human colorectal cancer cell lines (HCT116, HT-29, SW620, and DLD-1) ergosterol peroxide derived from Chaga, induced cell cycle arrest by reducing transcription of c-Myc, CDK-8, and cyclin D1 with increasing apoptosis induction." (PMID 37153767, 2023).
colorectal cancer (continued). "Surprisingly, in the ApcMin model, a murine model of colorectal cancer (CRC), CDK8 deletion shortens the survival of the mice and increasing tumor burden." (PMID 30693281, 2018). "Surprisingly, several reports have indicated that selective CDK8 inhibitors were inactive on colorectal cancer (CRC) cell lines with amplification of CDK8, which were previously characterized as being sensitive to CDK8 gene silencing." (PMID 28422713, 2017). "Indeed, chromosomal copy number gains in both CDK8 and RB1 loci on 13q in colorectal cancer cells provide a clear explanation of how they select optimal conditions to antagonise E2F1 suppressions." (PMID 32961708, 2020).
melanoma (26 papers, 2012 to 2026). A malignant, usually aggressive tumor composed of atypical, neoplastic melanocytes. "The loss of CDK8 in NK cells enhances the anti-tumor response against B16F10 melanoma cells and v-abl+ lymphoma cells." (PMID 38606172, 2024). "CDK8 overexpression was detected in a subset of melanoma cells with macroH2A loss and suppression of CDK8 inhibited the proliferation of melanoma cells." (PMID 33686962, 2021). "Genetic depletion of CDK8 in macroH2A1-deficient melanoma cells attenuated the proliferative advantage related to loss of macroH2A1." (PMID 34203934, 2021). "The malignant phenotype of macroH2A loss in melanoma but also other cancers was partially promoted by direct transcriptional upregulation of oncoprotein cyclin-dependent kinase 8 (CDK8)." (PMID 34203934, 2021). "An analysis of 36 melanoma patient samples revealed an inverse correlation between CDK8 and the histone variant macroH2A (mH2A) and a comparison of primary and metastatic melanoma samples showed a significant loss of mH2A upon invasiveness." (PMID 31248103, 2019). "Histone variant macroH2A suppresses melanoma progression via suppression of CDK8 expression and expression of macroH2A is generally lost with melanoma progression." (PMID 26426052, 2015). "Upregulation of CDK8 expression was also described in melanoma following loss of the histone variant macroH2A." (PMID 25625291, 2015). "This association has given rise to speculation that CDK8 drives the progression of melanoma by enhancing cell growth and migration." (PMID 31248103, 2019). "Reducing macroH2A expression directly activates cyclin-dependent kinase 8 (CDK8), which promotes the development of malignant melanoma." (PMID 39199381, 2024). "In malignant melanoma, mH2A was proven as a tumor suppressor gene in melanoma cells, with CDK8 possibly being the downstream target gene." (PMID 34120148, 2021). "It suppresses melanoma progression via transcriptional repression of CDK8, which is required for proliferation of melanoma cells." (PMID 32042336, 2020). "CDK8 expression was associated with shorter survival among cancers with below-median mutation burden, not only in AML but also in melanoma, ovarian adenocarcinoma and renal clear cell carcinoma." (PMID 31382571, 2019). "Metastatic melanoma tissues harbor a predominantly methylated mH2A2 promoter region and elevated CDK8 levels." (PMID 31248103, 2019). "Gene expression profiling of melanoma B16-F61 cells also found that decreased macroH2A1 levels correlate with a ≥2-fold change in the expression of cyclin-dependent kinase 8 (CDK8), a CRC oncogene." (PMID 31096699, 2019). "Activates CDK8 to promote the development of malignant melanoma." (PMID 39199381, 2024). "In both in vivo and in vitro experiments, reducing the expression level of MacroH2A1.2 could promote the progression of melanoma by increasing the expression of the CDK8 oncogene." (PMID 33858382, 2021). "CDK8 is also involved in the epigenetic changes in melanoma." (PMID 31248103, 2019). "In addition, macroH2A1 suppresses melanoma progression through downregulation of cyclin-dependent kinase 8 (CDK8) gene expression, which promotes cellular proliferation through enhancement of malignant transformation by β-catenin." (PMID 25003966, 2014). "The function of Cdk8 and the partially redundant Cdk19 protein kinase in humans are of considerable interest because a significant proportion of cancers may have alterations in their activity, particularly of melanoma and colorectal origin." (PMID 34849833, 2021). "Stratification into groups with high and low TMB revealed other cancers where CDK8 expression became a marker of shorter OS only in tumors with low TMB, namely melanoma, ovarian adenocarcinoma and renal clear cell carcinoma." (PMID 31382571, 2019).